KIAA0825 (KIAA0825)
Synonyms: C5orf36; DKFZp686F0372; MGC34713; PAPA10
Tractability: PROTAC: ubiquitination databases record sites on it.
Gene: Protein-coding gene on chromosome 5 (94,150,851 to 94,618,604, reverse strand). Ensembl gene ENSG00000185261.
Gene Ontology:
Molecular function: protein binding
Genetic constraint (gnomAD): Loss-of-function variants: 90 observed, 113.72 expected, observed/expected ratio (o/e) 0.79, 90% interval 0.67 to 0.94. The upper end of that interval is the gene's LOEUF score, 0.94, which puts it in group 4 of 6, group 1 being the genes least tolerant of losing a copy. Missense variants: 1,109 observed, 1,254.4 expected, observed/expected ratio (o/e) 0.88, 90% interval 0.84 to 0.93. Synonymous variants: 391 observed, 445.82 expected, observed/expected ratio (o/e) 0.88, 90% interval 0.81 to 0.95.
Homologues: Orthologues: chimpanzee KIAA0825 (96% identical), macaque KIAA0825 (92% identical), dog KIAA0825 (84% identical), rabbit KIAA0825 (80% identical), guinea pig KIAA0825 (79% identical), mouse 2210408I21Rik (72% identical), rat Kiaa0825 (68% identical), pig KIAA0825 (61% identical), tropical clawed frog KIAA0825 (42% identical).
Diseases named in the same sentence as KIAA0825 in open-access papers:
KIAA0825 is named in the same sentence as 2 diseases in open-access papers, as found by Europe PMC text mining. Sharing a sentence is not in itself a finding about the gene and the disease. The quoted sentences say what the papers report.
polydactyly (1 paper, 2025). A disease characterized by the presence of polydactyly, including syndromic and non-syndromic forms. "In this study, we identified three novel variants in KIAA0825 in unrelated families, strengthening the connection between this gene and polydactyly." (PMID 41010063, 2025).
Polysyndactyly (1 paper, 2023). Polysyndactyly or PPD4 is a form of preaxial polydactyly of fingers (see this term), a limb malformation syndrome, characterized by the presence of a thumb showing the mildest degree of duplication, being broad, bifid or with radially deviated distal phalanx. "We have identified the seventh novel variant in KIAA0825 causing polysyndactyly and clinodactyly." (PMID 37107627, 2023).